RETN (resistin)
Diseases named in the same sentence as RETN in open-access papers (continued):
Sharing a sentence is not in itself a finding about the gene and the disease.
liver disease (6 papers, 2015 to 2025). "In humans, resistin is predominantly produced by monocytes and macrophages and is associated with various diseases, including cardiovascular conditions, respiratory and liver diseases, and cancers." (PMID 39983655, 2025). "Hence, the suitability of systemic resistin levels as a non-invasive marker for liver diseases needs further study." (PMID 37238973, 2023). "However, an association of serum resistin amounts with histological parameters of liver disease severity could not be identified in patients suffering from chronic HCV infections." (PMID 37238973, 2023). "No studies are currently available on the relation between hepatic disease and resistin levels in dogs, additionally, to the authors knowledge, no studies are yet performed on the role of resistin in copper accumulation disorders." (PMID 33142854, 2020).
lung adenocarcinoma (6 papers, 2019 to 2025). A carcinoma that arises from the lung and is characterized by the presence of malignant glandular epithelial cells. "Evidence has linked increasing resistin expression with poor prognosis and the development of lung adenocarcinoma." (PMID 31719210, 2019). "Conversely, the expression of resistin in tumor tissue was found to be correlated with metastasis, particularly distant metastasis, and overall survival in lung adenocarcinoma." (PMID 40002704, 2025). "The Kaplan–Meier method was employed to explore the relationship between resistin expression in lung adenocarcinoma tissues and overall survival." (PMID 40002704, 2025). "Our previous study also demonstrated that resistin promotes lung adenocarcinoma metastasis through the TLR4/Src/EGFR/PI3K/NF-κB pathway." (PMID 40002704, 2025). "In our study, we explored resistin expression in lung adenocarcinoma and found a positive correlation with metastasis, particularly distant metastasis, and overall survival." (PMID 40002704, 2025). "In lung adenocarcinoma, our previous study demonstrated that resistin promotes metastasis via the TLR4/Src/EGFR/PI3K/NF-κB signaling pathway." (PMID 40002704, 2025). "Immunohistochemical analysis was conducted to detect the expression of resistin in 104 lung adenocarcinoma tissues." (PMID 40002704, 2025). "However, after adjusting for other variables in the multivariable analysis, only resistin expression emerged as an independent predictor of overall survival in lung adenocarcinoma patients (HR = 1.922, 95% CI = 1.008–3.393, p < 0.05)." (PMID 40002704, 2025). "Additionally, we found that the expression of resistin in tumor tissues correlated with metastasis (particularly distant metastasis) and overall survival in patients with lung adenocarcinoma." (PMID 40002704, 2025). "Another study has shown that resistin activates Toll-like receptor 4 (TLR4) and engages with the Src pathway which activated the EGFR phosphorylation and increased epithelial-mesenchymal transition (EMT), subsequently inducing the migration and invasion of lung adenocarcinoma." (PMID 33313320, 2020).
osteoporosis (6 papers, 2015 to 2025). A condition of reduced bone mass, with decreased cortical thickness and a decrease in the number and size of the trabeculae of cancellous bone (but normal chemical composition), resulting in increased fracture incidence. "Emerging evidence also suggests that resistin influences bone metabolism, disrupting the bone-muscle crosstalk crucial for maintaining musculoskeletal integrity and increasing the risk of osteoporosis and fractures, both key components of frailty." (PMID 39983655, 2025). "Therefore, single nucleotide variation in rs13144478 may lead to high serum resistin levels and low bone mineral density that may further increase the risk of osteoporosis in postmenopausal females." (PMID 35992125, 2022). "Therefore, single nucleotide variation in rs3931020 may lead to high serum resistin levels and low bone mineral density that may further increase the risk of osteoporosis in postmenopausal females." (PMID 35992125, 2022). "Thus, there may be an association between vitamin D and serum resistin levels that may further lead to osteoporosis development or progression, especially in postmenopausal females." (PMID 33519717, 2020). "In line with our results, another study found increased resistin levels in menopausal women with osteoporosis than a healthy group." (PMID 33519717, 2020). "It is essential to achieve a more precise explanation between vitamin D and resistin relationship so that new targets can be identified to treat osteoporosis." (PMID 33519717, 2020). "In the meantime, numerous studies have demonstrated altered levels of adiponectin and resistin in patients with osteoporosis." (PMID 26170530, 2015). "However, the results of a recent study showed that post-menopausal women with osteoporosis had higher serum resistin levels and low vitamin D with vitamin D as an independent predictor of serum resistin levels." (PMID 36831180, 2023). "The plausible cause for this could be that in osteoporosis, the proinflammatory cytokines such as serum levels of IL-6, leptin, IL-1, and resistin increases and might be the main contributing factor in the pathogenesis of osteoporosis." (PMID 33519717, 2020). "Previously, a number of human studies have suggested that adipokines, such as adiponectin, leptin, and resistin, might have a relationship with osteoporosis and BMD." (PMID 26170530, 2015). "The results conjecture that serum resistin levels are associated with BMD and rs3931020 and rs13144478 polymorphisms could be used together with other genetic markers to identify postmenopausal females at higher risk of developing osteoporosis." (PMID 35992125, 2022). "Research also showed that resistin, leptin, IL-1, IL-4, IL-6, and TGF-β played a significant role in postmenopausal women’s bone metabolism and could be used as a diagnostic marker capable of recognizing patients at risk of osteoporosis and thereby predicting the risk of fracture." (PMID 33519717, 2020). "A study stated that serum resistin has a negative correlation with osteocalcin, and when in osteoporosis levels of serum osteocalcin decreased in return, the levels of resistin increased." (PMID 33519717, 2020).
prediabetes (6 papers, 2020 to 2025). "Plasma adiponectin, visfatin, leptin, and resistin levels were measured in all the subjects, and the related risk factors of colonic polyps in prediabetes subjects were analysed." (PMID 32393372, 2020). "In this study, we investigated whether changes in plasma adiponectin, visfatin, leptin, and resistin levels are associated with the onset of colonic polyps in prediabetes subjects." (PMID 32393372, 2020). "Until now, the correlation between plasma adiponectin, visfatin, leptin, and resistin levels and the incidence of colonic polyps in the prediabetes population, as well as the number and degree of malignant polyps in the colon, is still unclear." (PMID 32393372, 2020). "This research explores the relationship between plasma adiponectin, visfatin, leptin, and resistin levels and the development of colonic polyps in prediabetes subjects." (PMID 32393372, 2020). "Research indicates that individuals with prediabetes exhibit elevated levels of multiple inflammatory markers, including resistin, interleukin-6 (IL-6), TNF-α, interleukin-1β (IL-1β), and monocyte chemoattractant protein-1 (MCP-1), in their serum along with high fasting blood glucose levels." (PMID 39634176, 2024). "In addition, we demonstrated that plasma visfatin and adiponectin levels but not plasma leptin and resistin levels are closely associated with the development of colonic polyps in prediabetes subjects." (PMID 32393372, 2020).
acne vulgaris (5 papers, 2018 to 2021). "The reviewed articles reported that RETN (resistin) SNPs − 420 C/G and + 299 G/A were significantly associated with the risk of acne and more severe forms of acne, while the—− 20/ + 299 GA haplotype was significantly associated with the risk of acne." (PMID 33849530, 2021). "It is discovered that the RETN gene polymorphisms that influence the level of resistin expression are closely associated with acne vulgaris, and those individuals with variant RETN genotypes have lower HDL-C levels." (PMID 34466520, 2019). "A previous study showed that rs1862513 SNP in the RETN gene was strongly associated with familial acne vulgaris in patients from Pakistan." (PMID 29584687, 2018). "Previous literature has shown an association between rs3745367 and other polymorphisms in the RETN gene with acne vulgaris development." (PMID 29584687, 2018). "Extending the present study in future investigation to include other polymorphisms in the RETN gene such as rs1862513 that has been shown to be associated with acne is strongly recommended." (PMID 29584687, 2018). "In the available genetic studies, the resistin gene rs1862513 (+299G > A) and rs3745367 (−420C > G) polymorphisms were strongly associated with familial acne vulgaris and the severity of symptoms but not with the acne types." (PMID 33260746, 2020).
acute kidney injury (5 papers, 2009 to 2019). Sudden and sustained deterioration of the kidney function characterized by decreased glomerular filtration rate, increased serum creatinine or oliguria. "Septic hyperresistinemia (plasma resistin >20 ng/ml) has been associated with greater disease severity and worse outcomes, and it is further exacerbated by concomitant acute kidney injury (AKI)." (PMID 28779451, 2017). "Renal failure was associated with elevated serum resistin, as resistin correlated with creatinine (r = 0.462, P < 0.001) and cystatin C (r = 0.442, P < 0.001)." (PMID 19545363, 2009). "Visfatin levels correlated with biomarkers of renal failure, liver dysfunction, and other adipokines (e.g., resistin, leptin, and adiponectin) in critically ill patients." (PMID 30224938, 2018). "Serum resistin concentrations were closely correlated to inflammatory parameters such as C-reactive protein, leukocytes, procalcitonin, and cytokines such as IL6 and TNF-α, as well as associated with renal failure and liver synthesis capacity." (PMID 19545363, 2009). "Our group and others have shown that resistin, an inflammatory molecule and well-known uremic toxin, is elevated during septic shock, especially in patients with concomitant acute kidney injury (AKI)." (PMID 28779451, 2017).
atrial fibrillation (5 papers, 2019 to 2025). A disorder characterized by an electrocardiographic finding of a supraventricular arrhythmia characterized by the replacement of consistent P waves by rapid oscillations or fibrillatory waves that vary in size, shape and timing and are accompanied by an irregular ventricular response. "Prospective cohort studies demonstrate that elevated resistin concentrations independently predict incident atrial fibrillation after adjustment for established cardiovascular risk factors." (PMID 41347124, 2025). "An analysis that included data from 34 studies involving 31,479 patients showed that adipokines, mainly adiponectin, apelin, and resistin, are associated with the risk of developing atrial fibrillation." (PMID 40725736, 2025). "Regarding CVD, elevated resistin values have been associated with ventricular dysfunction and atrial fibrillation risk, due to resistin’s capability of triggering myocardial fibrosis." (PMID 37238961, 2023). "The proinflammatory effect of resistin in plasma is linked to more frequent incidents of atrial fibrillation in the general population." (PMID 36624488, 2023). "The higher concentrations of resistin in PVAT near the left main coronary artery which is located close to the left atrium are associated with postoperative atrial fibrillation." (PMID 31842758, 2019). "The main finding of the study is that higher concentration of resistin close to the left main trunk is associated with the occurrence of postoperative atrial fibrillation." (PMID 31842758, 2019). "Additionally, greater genetically predicted resistin levels are significantly related to a raised atrial-fibrillation risk." (PMID 37238961, 2023). "The aim of the study is to assess whether of PVAT resistin concentration in patients undergoing coronary artery bypass grafting (CABG) is associated with the occurrence of postoperative atrial fibrillation." (PMID 31842758, 2019). "The analysis of the ROC curves showed that the highest predictive value of the compared parameters of postoperative atrial fibrillation was the level of PVAT resistin, followed by the plasma resistin level." (PMID 36624488, 2023). "The analysis of the ROC curves shows that determining the level of resistin in PVAT is the best biomarker of postoperative atrial fibrillation in patients undergoing CABG." (PMID 36624488, 2023). "Resistin is known to be a proinflammatory cytokine and many studies indicate a relationship between higher plasma concentration of resistin and occurrence of atrial fibrillation." (PMID 31842758, 2019). "The multivariate stepwise logistic regression analysis revealed that only resistin concentration in PVAT close to the left main trunk higher than 54 ng/g is related with postoperative atrial fibrillation occurrence (OR: 7.7; 95% CI 1.4–42.2 p = 0.02)." (PMID 31842758, 2019). "Higher resistin concentration in PVAT near to the trunk of left coronary artery which is located close to the left atrium is related to atrial fibrillation occurrence after CABG." (PMID 31842758, 2019). "The Framingham Offspring Study showed that higher plasma levels of resistin were related to higher incidence of atrial fibrillation in the general population." (PMID 31842758, 2019). "Our study primarily has a cognitive value indicating the local effect of resistin concentration, as a proinflammatory factor, in triggering post-operative atrial fibrillation." (PMID 31842758, 2019). "The cut off point for the concentration of resistin which has the best sensitivity and specificity to predict postoperative atrial fibrillation occurrence was determined at 54 ng/g." (PMID 31842758, 2019). "They examined 40 patients after CABG and revealed that postoperative elevated C-reactive protein and resistin serum levels were significantly higher in patients with postoperative atrial fibrillation." (PMID 31842758, 2019).
atrial fibrillation (continued). "Higher concentration of resistin near the trunk of left coronary artery is related with occurence of postoperative atrial fibrillation." (PMID 31842758, 2019). "In postoperative settings, resistin measured in perivascular adipose tissue surrounding coronary arteries demonstrates superior predictive accuracy for postoperative atrial fibrillation following cardiac surgery compared to plasma resistin concentrations or conventional inflammatory markers." (PMID 41347124, 2025). "Elevated levels of plasma resistin, which reflect PVAT resistin levels in patients qualified for myocardial revascularisation, may be associated with postoperative atrial fibrillation complications." (PMID 36624488, 2023). "Moreover, in this study, only serum resistin level was the independent factor of atrial fibrillation after CABG." (PMID 31842758, 2019). "In the multivariate stepwise logistic regression analysis the concentration of resistin above cut-off point 54 ng/g in PVAT near left main coronary artery was independently related to postoperative atrial fibrillation occurrence (OR: 7.7; 95% CI:1.4–42.2 p = 0.02)." (PMID 31842758, 2019). "The aim of the study was to evaluate whether concentration of resistin in surrounding coronary artery perivascular adipose tissue (PVAT) is related to postoperative atrial fibrillation occurrence." (PMID 31842758, 2019). "The concentration of resistin in PVAT near the left main coronary artery was significantly higher in patients with postoperative atrial fibrillation than in those without the complication (P = 0.03)." (PMID 31842758, 2019). "Plasma resistin levels are derived from many areas of adipose tissue due to many reasons including surgical stress, but it does not lead to postoperative atrial fibrillation in all patients with visceral obesity." (PMID 31842758, 2019). "It is not known whether increased resistin concentration in PVAT is related to postoperative atrial fibrillation." (PMID 31842758, 2019). "Therefore, the level of plasma resistin in patients with advanced CAD could be indicative of the condition of epicardial adipose tissue and thus have an impact on the frequency and severity of postoperative complications in the form of paroxysmal atrial fibrillation." (PMID 36624488, 2023).
Dengue fever (5 papers, 2016 to 2023). "Obesity-induced leptin and resistin are known to be associated with many of the physiological abnormalities seen in dengue, including platelet dysfunction, vascular inflammation, myocardial injury, endothelial dysfunction, and capillary hyper-permeability." (PMID 33083561, 2020). "Plasma resistin was elevated in the early phase of acute Dengue fever, but associations with kidney function or other disease severity markers were not reported." (PMID 30517161, 2018). "Higher levels of neutrophil gelatinase-associated lipocalin (NGAL) and resistin were detected in dengue patients with normal leukocyte count and all dengue patients, respectively." (PMID 27549428, 2016). "Moreover, plasma resistin levels are elevated in acute Dengue fever and Crimean-Congo hemorrhagic fever, and plasma resistin levels also associate with severe disease." (PMID 35062248, 2021). "NGAL and resistin were novel dengue-associated molecules while NGAL might associate with anti-dengue immune responses and resistin might be a novel biomarker for dengue infection." (PMID 27549428, 2016). "In contrast, serum resistin level was similar in the groups of dengue patients classified by the presence of leukopenia or thrombocytopenia." (PMID 27549428, 2016). "Our results revealed that resistin and NGAL are novel dengue-associated molecules." (PMID 27549428, 2016). "Increased serum level of resistin was observed in dengue patients." (PMID 27549428, 2016). "The present study showed that serum resistin level significantly increased in dengue patients." (PMID 27549428, 2016). "We determined the levels of leptin, resistin, omentin, adiponectin, IFNβ, and NS1 in patients with dengue fever (DF) and dengue haemorrhagic fever (DHF) at admission (febrile phase) and at the critical phase." (PMID 37676889, 2023). "Serum levels of MIF, sVCAM-1, sFasL, resistin and IFN-γ in dengue patients were significantly higher than those in healthy controls." (PMID 27549428, 2016). "Our results showed the serum concentrations of MIF, sVCAM-1, sFasL, resistin, and IFN-γ were significantly higher in dengue patients than that in healthy controls." (PMID 27549428, 2016). "We determined the levels of leptin, resistin, omentin, adiponectin, as well as IFNβ, and NS1 using quantitative ELISA in patients with dengue fever (DF = 49) and dengue haemorrhagic fever (DHF = 22) at admission (febrile phase) and at the time of discharge (recovery phase)." (PMID 37676889, 2023). "Further analyses showed that serum level of NGAL, but not resistin, was correlated with leukocyte and platelet count in dengue patients." (PMID 27549428, 2016). "It suggests that serum resistin and sFasL might be potential biomarkers for dengue infection since MIF is correlated with disease severity and clinical outcome in dengue." (PMID 27549428, 2016). "Furthermore, the serum level of NGAL, but not resistin, was correlated with cell count in dengue patients." (PMID 27549428, 2016).